ALK (ALK receptor tyrosine kinase)
Diseases named in the same sentence as ALK in open-access papers (continued):
Sharing a sentence is not in itself a finding about the gene and the disease.
tumor (2,254 papers, 2004 to 2026). "After an ALK mutation was identified in the primary tumor tissue using the Pillar OncoReveal Multi-Cancer CNV RNA Fusion Panel, lorlatinib was initiated." (PMID 41948498, 2026). "Clusters 4 and 5 demonstrated high expression of ALK alterations and tumor suppressor gene mutations (n = 31 and n = 25, respectively)." (PMID 41975817, 2026). "Studies have shown that ALK mutations are associated with larger tumor diameters and higher solid component proportions, which was confirmed in this study, although no significant statistical differences were observed due to the small sample size." (PMID 41378298, 2025). "This molecular cascade links ALK mutational activation to both EMT phenotype acquisition and clinically observed aggressiveness in ALK-rearranged tumors, indicating that this mutation promotes tumor progression and augments its metastatic potential." (PMID 40568576, 2025). "In 2930 patients with 11 tumor types treated with immune checkpoint inhibitors, the mutation of ALK indicated favorable overall survival (hazard ratio = 0.69; 95% confidence interval, 0.57-0.83; p < 0.001)." (PMID 41716637, 2025). "Despite initially responding to crizotinib and alectinib, the predominant tumor clone containing the ALK G1269A mutation was overtaken by the one with G1202R." (PMID 40168046, 2025). "A variety of ALK gene alterations, including ALK fusion, point mutations, and amplification, have been identified across various tumor types." (PMID 40234387, 2025). "These tumours commonly show diffuse immuno-expression of cytokeratin (CK) and anaplastic lymphoma kinase (ALK), which poses a diagnostic challenge." (PMID 41497928, 2025). "For instance, drugs targeting ALK (Anaplastic Lymphoma Kinase) mutations can be selectively used to inhibit tumour growth and reduce the side effects associated with traditional chemotherapy and radiotherapy." (PMID 40098211, 2025). "In terms of ALK mutations, previous studies have shown that ALK gene fusion is associated with larger tumor volumes and higher solid component proportions." (PMID 41378298, 2025). "NGS can identify actionable mutations, such as EGFR, KRAS, and ALK mutations, that drive tumor growth, enabling more precise and effective treatment decisions." (PMID 39796742, 2025). "Another promising approach is oncolytic virotherapy, which aims to selectively lyse ALK-rearranged tumor cells, thereby releasing tumor-associated antigens and activating immune responses within the tumor microenvironment." (PMID 40894217, 2025). "Mutations in the ALK gene can lead to the aberrant activation of the ALK protein, resulting in uncontrolled cell growth and tumor formation." (PMID 41246301, 2025). "This supports the concept that the underlying tumor biology drives prothrombotic risk, which is further supported by previous data linking ALK-rearrangement to tumoral tissue factor expression." (PMID 40896464, 2025). "One patient had an ALK-amplified tumor with concurrent subclonal ALK R1192W oncogenic mutation (VAF 0.1%)." (PMID 40036726, 2025). "Here, we analyze mutational profiles of tumor tissue or liquid biopsy samples from real‐world ALK‐positive NSCLC patients who had relapsed on first‐ or second‐line alectinib treatment to elucidate potential resistance mechanisms." (PMID 40168046, 2025). "Despite the identification of numerous molecular markers related to NSCLC, including EGFR mutations and ALK fusions, their expression is highly heterogeneous across patients and tumor subtypes, limiting their general applicability." (PMID 40055838, 2025). "During the disease progression, circulating tumor DNA (ctDNA) sequencing revealed the emergence of ALK L1196M mutation, which demonstrated sensitivity to brigatinib." (PMID 40160872, 2025).
tumor (continued). "Other studies have shown that ALK-positive tumors are less likely to exhibit cavity signs and air bronchograms, and are associated with larger tumor size and a higher proportion of solid components." (PMID 41378298, 2025). "Two patients with EGFR-mutated and ALK-rearranged tumor had received tyrosine kinase inhibitors previously." (PMID 39850629, 2025). "ALK mutations are also frequently found in HRNB, and ALK amplification is independently associated with aggressive tumor features such as tumor progression and therapy resistance." (PMID 40104501, 2025). "Another relevant immune subpopulation in ALCL are tumor-associated macrophages (TAMs), with differences between ALK+ and ALK- ALCLs." (PMID 40565334, 2025). "Emerging evidence suggests that somatic mutations in driver genes can modulate tumor immunogenicity; for example, ALK rearrangements, EGFR mutations, and KRAS mutations correlate with immunosuppressive tumor microenvironments (TMEs)." (PMID 40873541, 2025). "Targeted therapy was administered to patients whose tumours harboured ALK or EGFR mutations, in accordance with the local reimbursement policy, in 6% of cases." (PMID 40650126, 2025). "Mutations in ALK, such as F1174L and R1275Q, lead to constitutive activation of pro-survival pathways or receptor amplification, driving sustained tumor growth, cell proliferation, and migration." (PMID 40129921, 2025). "We only detected minor clones with ALK resistance mutations evolving into the dominant resistant mutation in cases where the relapses occurred at the same tumor location as the pre-treatment sample." (PMID 40227636, 2025). "Our aim was to assess if the presence of ALK-resistance associated mutations in the tumor tissue before the start of first or subsequent lines of ALK-inhibitor therapy was predictive for the resistance mechanism." (PMID 40227636, 2025). "Crizotinib showed the ability to inhibit growth and enhance apoptosis in tumor cell lines containing ALK fusion variants (EML4-ALK or NPM-ALK)." (PMID 40149618, 2025). "In conclusion, the development of ALK-TKI resistance is associated with increased PD-L1 expression in both tumor and stromal compartments, a functional deficit in CD8+ T cell cytolytic activity despite their presence, and a significant increase in Treg cells." (PMID 40058234, 2025). "Here, we conducted a comprehensive bioinformatic and clinical analysis on the characteristics of pan-cancer ALK mutation and its association with tumor immunity and the efficacy of immune checkpoint blockade." (PMID 41716637, 2025). "Molecular analysis of tumor tissue from patient P3 documented the TERT rearrangement breakpoint as well as the previously reported ALK p.R1275Q mutation." (PMID 39760332, 2025). "We report long-lasting clinical responses in five patients treated with lorlatinib, four of which harbored somatic ALK variants that permitted longitudinal monitoring of tumor burden." (PMID 39177282, 2024). "The studies evaluated show that its heterogeneity varies with the mutation type (EGFR, ALK), tumor stage, distribution of histological subtypes, and frequency of co-alterations." (PMID 39001401, 2024). "These mutations, occurring independently within the tumor, significantly reduce the effectiveness of different ALK inhibitors." (PMID 38927911, 2024). "MYCN amplification, ALK mutations, chromosomal abnormalities, changes in the pattern of DNA methylation, and tumor microenvironment are the primary molecular features in HRNBs." (PMID 38601081, 2024). "It is finally reported that some specific variants of ALK fusions are null fusions, meaning they are unable to translate tumor-causing kinesins." (PMID 39063924, 2024).
tumor (continued). "In some cases, secondary mutations have been found in the EML4-ALK gene within tumor cells from patients who relapsed after ALK inhibitor treatment." (PMID 38927911, 2024). "NB is characterized by significant genetic alterations, notably MYCN amplification and ALK mutations, which play pivotal roles in tumor initiation." (PMID 39458991, 2024). "(2018) conducted PD-L1 detection with the 22C3 Assay on 10005 NSCLC patients, and the results showed that poorly-differentiated tumor histology and ALK translocation were significantly associated with PD-L1 expression." (PMID 38835380, 2024). "ALK-positive (ALK+) tumors can evade the immune system, partly through tumor-associated macrophages (TAMs) that facilitate immune escape." (PMID 39767726, 2024). "The predictive efficacy of ctDNA varies according to the mutation type (e.g., EGFR, ALK), tumor stage, and histological subtype distribution." (PMID 39001401, 2024). "This exploratory analysis included randomization (1:1) of patients with EGFR and ALK mutations, stratified by PD-L1 tumor cell (TC) expression (≥25% vs. <25%)." (PMID 38927911, 2024). "This patient’s tumor cells showed high ALK expression, but it remained unclear if an ALK variant was present." (PMID 38168093, 2024). "As a rare genetic variant, identification of this tumor’s ALK alteration was only elucidated via NGS, and ultimately precipitated an exceptional response for this patient." (PMID 39659799, 2024). "ALK gene testing showed that 13 of the 30 patients with tall column‐shaped tumour cells presented with mutation in the ALK gene, whereas 8 of the 30 patients with quasi‐circular tumour cells presented with mutation in the ALK gene." (PMID 38616354, 2024). "For instance, the overexpression of the MYCN gene results in the inhibition of apoptotic signaling and induction of cell proliferation, and activating mutations in ALK promotes tumor growth, proliferation, and migration." (PMID 39338204, 2024). "Due to tumor cell heterogeneity, post-progression tumor tissues utilize diverse ALK inhibitor resistance pathways, and new diagnostic techniques are needed to understand resistance mechanisms and provide the best treatment." (PMID 37322261, 2024). "Specifically, crizotinib, which targets IMT with a positive ALK gene mutation, has been shown to induce tumor shrinkage and enhance the outcomes of surgical interventions." (PMID 38310322, 2024). "ALK gene testing also showed that two morphologically different cell types had different rates of mutation in the ALK gene: goblet‐like tumour cells has a significantly higher rate of mutation in the ALK gene than quasi‐circular tumour cells." (PMID 38616354, 2024). "The next-generation sequencing has shown PIK3CA E545K, SMAD4 1309-1G, and ALK E717K gene mutations, receptor tyrosine kinase 2 (ErbB-2) amplification, microsatellite stability, and low tumor mutational burden of 6.3 mutations per megabase." (PMID 38215117, 2024). "When the Anaplastic Lymphoma Kinase (ALK) is mutated and abnormally activated, it often alters its own kinase activity, thereby activating downstream signaling pathways and leading to tumor development." (PMID 38762484, 2024). "The association between ALK rearrangement and immune cells is complex and contingent on the specific characteristics of the tumor microenvironment." (PMID 38397899, 2024). "The ALK variant allele frequency (VAF) was available for 33 of the enrollment tumor sequencing results and ranged from 2% to 57%, with nine having ALK VAF < 20%." (PMID 37012551, 2023). "In this study, 21 patients with various tumor types harboring ALK aberrations (10 patients with ALK gene rearrangement and 11 with ALK mutation or amplifications) were treated with alectinib." (PMID 37773318, 2023). "We posit that, due to intra-tumor heterogeneity and clonal evolution, mutations in ALK are branched events in these patients and that lorlatinib monotherapy will be insufficient." (PMID 37012551, 2023).
tumor (continued). "Several studies have shown that high tumour PD-L1 expression is linked to worse progression-free survival (PFS) in response to ALK-TKIs." (PMID 37371571, 2023). "Similar to other studies, we demonstrated that tumour-associated PD-L1 expression correlated with increased Treg infiltration in ALK-rearranged NSCLC." (PMID 37371571, 2023). "Together, these data show that although there is ongoing clonal evolution upon xenotransplantation, the PDX maintains the landscape of somatic mutations and oncogenic drivers displayed in its parental ALK+ ALCL tumour." (PMID 37357529, 2023). "The ALK fusion gene is another important tumor driver gene found in NSCLC after mutations in the epidermal growth factor receptors." (PMID 36903251, 2023). "Several reports have provided evidence of the efficacy of TKIs such as erlotinib and gefitinib for EGFR mutation-positive cancers and crizotinib for tumours harbouring ALK rearrangements." (PMID 37686122, 2023). "To examine the spectrum of ALK mutations in our cohort, we analyzed germline and somatic ALK point mutations in blood, BM-infiltrating NB cells and NB tumor tissue samples." (PMID 36765519, 2023). "Entrectinib also displays promising anti-tumor activity in NB, evinced by diminished Ki-67 and activation of caspase-3 in ALK wild-type, amplified or mutated cell lines." (PMID 36839989, 2023). "Reconstruction of the clonal evolution of this tumor revealed that all ALK mutations and the HRAS alteration had developed from the same ancestral clone C0." (PMID 36807339, 2023). "In the 37 patients with detectable baseline ctDNA, using the FoundationOne Liquid CDx27, ALK mutations detected in patient plasma at study entry were identical to the alterations seen in the tumor tissue used for study eligibility." (PMID 37012551, 2023). "ALK inhibitors are a group of tyrosine kinase inhibitors (TKI) targeting tumor cells expressing oncogenic mutations on the ALK." (PMID 37072555, 2023). "One infant under 6 months of age, with favorable INPC histopathology, SCA genomic profile, and ALK mutation remains alive with residual tumor mass over 5 years after diagnosis." (PMID 36865795, 2023). "The drug was well tolerated as a single agent, eliciting an objective tumor response in 3 out of 11 NB ALK-mutated patients (2 stable disease (SD) and 1 complete response (CR))." (PMID 36765519, 2023). "I1461V, K1491R, and D1529E ALK variants, estimated as benign variants in ClinVar, were also detected in all tumour samples from onset to the second relapse." (PMID 36819147, 2023). "Gene fusions, chromosomal translocations, gene amplification or deregulation, and activating point mutations are the three main ways by which ALK signaling is triggered in tumor cells." (PMID 37568193, 2023). "Secondary ALK inhibitor resistance mutations were previously identified in 20–30% of tumor samples with crizotinib failure." (PMID 36768562, 2023). "The mechanism of action of drugs that inhibit ROS1 is similar to that of ALK inhibitor drugs, and they can cause tumor cells to shrink." (PMID 37901797, 2023). "Tumor tissue for CLIA-certified sequencing of ALK came from diagnostic tumor or primary tumor resections in ten (25%) relapsed and five (55%) refractory patients and from biopsies at time of relapsedrefractory disease for the remainder of patients." (PMID 37012551, 2023). "Further studies detected multiple resistance mutations responsible for the treatment failure with ALK-TKI including the I117N which confers tumor resistance to alectinib." (PMID 36786970, 2023). "NPM::ALK regulates the transcriptional silencing of many gene promoters and enhancer regions that encode tumor suppressors through its downstream effector transcription factors." (PMID 37810974, 2023). "According to a recent study, gilteritinib was effective in inhibiting ALK L1256F‐mutated tumours, previously found to be insensitive to lorlatinib." (PMID 37149843, 2023).
tumor (continued). "While the F1174S mutation has not previously been reported in NSCLC, it has been shown to correlate with aggressive tumor progression in a relapsed NB harboring a F1174S mutation in full length ALK." (PMID 38264745, 2023). "Using human tumor biological samples, they further demonstrated that the expression of phosphorylated ALK (p-ALK) was associated with resistance to PARP inhibitors and positively correlated with the expression of p-Tyr19-CDK9." (PMID 36611214, 2023). "RNA sequencing analysis revealed that the large‐sized tumour cells of the pulmonary tumour had acquired L1196M mutation in the ALK gene." (PMID 36819147, 2023). "In detail, EGFR overexpression, observed in 68% of cases, was correlated with tumor aggressiveness (p = 0.049), while ALK low expression in 92% was associated with stage (p = 0.048)." (PMID 35406495, 2022). "Genetic alterations of ALK, including point mutations, deletions, and rearrangements, have been described in a range of tumor types and tumorigenesis." (PMID 36128740, 2022). "A recent study showed that heterogeneous pretreatment tumor evolution was closely associated with rapid alectinib resistance in ALK-rearranged NSCLC21." (PMID 35042943, 2022). "The two groups were similar in terms of age, sex, smoking history, ECOG PS, histologic subtype, EGFR and ALK tumor mutation status, PD-L1 TPS score and pretreatment NLR." (PMID 35627534, 2022). "To date, the gold standard for measuring EGFR and ALK status is mutational sequencing of tumor tissue acquired from biopsy." (PMID 35624472, 2022). "Significant association was also observed between tumor grade and ALK fusion, and post hoc analysis showed that ALK fusion was significantly more prevalent in grade II tumors compared to grade IV tumors." (PMID 35061839, 2022). "We aimed to use artificial intelligence (AI) models to predict EGFR mutations and ALK rearrangement status using common demographic features, pathology and serum tumor markers (STMs)." (PMID 35624472, 2022). "Thirty-six tumour-related genes including ALK, AR, BRCA2, FANCD2 and CBL were found to be mutated in all the three disease groups." (PMID 36686473, 2022). "The CLTC–ALK fusion gene has been shown to be an ALK activator in large B-cell lymphoma and is associated with tumor recurrence." (PMID 35686089, 2022). "Meanwhile, an ALK F1245C mutation promotes resistance to the first-generation ALK inhibitor, crizotinib, while G1202R is the most common mutation observed in tumours resistant to second generation ALK TKIs." (PMID 35884511, 2022). "It was shown that spectral CT has the potential to predict KRAS and EGFR mutations as well as ALK reordering in solid lung adenocarcinoma, thus accurately reflecting molecular features of this tumour." (PMID 35406429, 2022). "Hotspot mutations in the ALK gene were identified in tumor samples from five of these high-risk NBL patients." (PMID 36037157, 2022). "To validate their tumor association, we overlapped the cfDNA-derived DMRs to differentially methylated sites found by comparing ALK-positive tumor tissue to normal lung tissue." (PMID 36461127, 2022). "The histogram and texture categories served as the foundation for the radiomic model, which implies that the intensity change of tumours was a potent predictor of the ALK genetic mutation." (PMID 36338735, 2022). "In February 2020, tumor growth was noted again at several sites, along with detection of ALK:p.L1196M/p.G1202R and p.L1196M/p.D1203N compound mutations." (PMID 36207130, 2022). "Owing to the characteristics of ALK expression in the body, it has long been considered a potential tumor-associated antigen (TAA)." (PMID 35958559, 2022).